BDNF (brain derived neurotrophic factor)
Diseases named in the same sentence as BDNF in open-access papers (continued):
Sharing a sentence is not in itself a finding about the gene and the disease.
depression (continued). "In the domain of epigenetics, the methylation status of the BDNF promoter region is pivotal, as it can modulate BDNF release, subsequently influencing depression risk." (PMID 38377025, 2024). "Visual episodic memory and new learning as measured by PALTEA were associated with the BDNF rs6265 Met/Met genotype (slope = 7.25, p < 0.001), age (slope = 0.21, p < 0.001), and depression (slope = 0.12, p = 0.02)." (PMID 38379321, 2024). "The Val66Met polymorphism, which involves the substitution of valine (Val) with methionine (Met) at codon 66, affects BDNF secretion and has been linked to various neuropsychiatric conditions, including depression." (PMID 39355088, 2024). "Brain-derived neurotrophic factor (BDNF) plays a role in regulating hippocampal plasticity, and its deficiency is implicated in the pathophysiology of depression." (PMID 39444807, 2024). "According to the synaptic plasticity theory, depression is closely associated with downregulation of brain-derived neurotrophic factor (BDNF)." (PMID 39371910, 2024). "Working memory and executive function as assessed by SWMBE468 were associated with the BDNF rs6265 Met/Met genotype (slope = 6.92, p = 0.01), age (slope = 0.35, p < 0.001), and depression (slope = 0.19, p = 0.003)." (PMID 38379321, 2024). "The findings indicated that 41 elderly individuals were diagnosed with depression, which was associated with a decrease of irisin and BDNF levels in CSF, comparable to the observed outcomes in dementia patients." (PMID 38985081, 2024). "One such example is depression, where there are conflicting reports on the role of BDNF as a biomarker or on the role of the BDNF-Val66Met polymorphism in major depressive disorder where differences between Caucasian and Asian populations have been reported." (PMID 39204102, 2024). "SNPs of the microRNA146a gene at rs2910164, the ACE2 gene at the rs2285666 and the SGK1 gene at rs1743963 and rs1763509, and the SNPs at the 5-HTTLPR and BDNF gene loci are associated with the onset of comorbid depression in coronary heart disease." (PMID 38745947, 2024). "Memory and cognitive impairment are the core features of depression, which are associated with BDNF level and neuronal apoptosis." (PMID 38178196, 2024). "A recent study explored the dose–response effect of mindfulness-based therapy for anxiety and depression and the increase in BDNF, which this paper views as associated with neurogenesis." (PMID 39684635, 2024). "Altered BDNF levels are associated with increased appetite, obesity, type 2 diabetes, schizophrenia, depression, and neurodegenerative diseases, including Alzheimer’s disease." (PMID 38559694, 2024). "In humans, the BDNF Val66Met polymorphism can contribute to increased body weight, major depression, reductions in the size of brain areas and declines in memory capacity." (PMID 38534429, 2024). "Low levels of BDNF have been associated with mood disorders such as depression, while increased BDNF levels have been linked to improved mood and resilience to stress and negative emotions in aging adults." (PMID 39656488, 2024). "‘Working memory and executive function’ as assessed by SWMBE468 was associated with the BDNF rs6265 Met/Met genotype (slope = 6.71, p = 0.01), age (slope = 0.32, p < 0.001), and depression (slope = 0.20, p = 0.002)." (PMID 38379321, 2024). "Research has consistently shown a strong association between reduced BDNF levels and the development of depression." (PMID 39194700, 2024). "It is well known that LPS- associated neuroinflammation reduces hippocampal BDNF expression, exerting depression-like behavioral changes, and intensifies hippocampal long-term depression (LTD)." (PMID 38542177, 2024). "Conversely, prenatal BDNF expression is downregulated by factors such as viral infection or other stressors, including depression and estrogen deficiency." (PMID 39655343, 2024).
depression (continued). "Abnormal methylation of certain alleles within the six CpG sites has been identified as a contributor to atypical BDNF expression and has been implicated in depression, suggesting a potential connection between epigenetic regulation and MDD." (PMID 39194576, 2024). "For example, increasing the activity of HPA and reducing estradiol cause dysfunction of the BDNF signaling pathway, which leads to depression." (PMID 37953501, 2024). "Glucocorticoids, including corticosterone, interact with BDNF in the brain to modify synapses and these interactions are associated with stress and depression resilience." (PMID 41311864, 2024). "This is confirmed by our detection of increased serum IL-6, TNF-α, CRH, and CORT levels as well as decreased hippocampal BDNF expression in depression-like mice, these results are both caused by depression and in turn can exacerbate depression." (PMID 39494347, 2024). "In the present study, we investigated association between levels of IL-4, BDNF, neopterin and depression in lymphoma patients receiving consecutive cycles of chemotherapy." (PMID 39355088, 2024). "Studies have shown that decreased BDNF levels are associated with cognitive impairment and depression in patients with cancer." (PMID 39355088, 2024). "The BDNF Val66Met is a risk gene polymorphism that adversely influences the clinical progression of AD, and it is also a risk factor for late-life depression." (PMID 38279143, 2024). "Research described in this review clearly indicates that both early-onset and late-onset depression are associated with altered BDNF expression." (PMID 39598521, 2024). "Disruptions in either system can exacerbate mood disorders, with depressive symptoms often associated with lower BDNF levels and altered serotonin levels that vary between depression and BD, reflecting their different roles in these conditions." (PMID 39493096, 2024). "The Val66Met allele of brain-derived neurotrophic factor has also been identified as increasing the risk for depression in AD." (PMID 39767653, 2024). "As already mentioned, acute sleep loss is famed for its rapid, albeit transient antidepressant effect in patients with depression, which has long been linked to BDNF increase." (PMID 38519465, 2024). "Mutations in the BNDF gene leads to a decrease of BDNF secretion, leading to a volume reduction of a specific brain area, impaired situational memory function, and higher risk of anxiety and depression." (PMID 38985081, 2024). "The efficacy of paroxetin, a selective serotonin reuptake inhibitor (SSRI), in AD-related depression has been shown to depend on the BDNF G196A gene polymorphisms, since A allele carriers display better therapeutic response." (PMID 38995015, 2024). "Despite genetics and inflammation, outcomes of recent studies indicate also the possible impact of the BDNF signaling pathway on the association of insomnia and depression in the OSA." (PMID 38495904, 2024). "Among these factors, BDNF is differentiated by its role in memory functions, neurogenesis, and structural maintenance; its deficit has been associated with depression and neurodegeneration." (PMID 38707461, 2024). "The neurotrophic theory of depression posits that environmental stress factors and mutations decrease BDNF synthesis in the brain, leading to reduced synaptic plasticity, decreased synaptic transmission, and increased neuronal degeneration." (PMID 39598521, 2024). "This has also been associated with BDNF influences on GABAergic neuronal synapses, and decreased levels of this neurotrophic molecule have been associated with anxiety and depression." (PMID 39684475, 2024). "The relationship between Met allele carrier status, BDNF levels, and depression has been extensively studied, but the interpretation of peripheral BDNF levels remains challenging due to significant methodological variations." (PMID 39596555, 2024).
depression (continued). "BDNF, the most abundant neurotrophin in the brain, is closely associated with anxiety and depression." (PMID 38988101, 2024). "In turn, a decrease in BDNF levels/signaling is considered a risk factor in depression pathogenesis and a consistent biomarker in mood disorders." (PMID 39769243, 2024). "Numerous studies have shown that BDNF is closely associated with the occurrence, development, and treatment of depression." (PMID 38628641, 2024). "The occurrence of depression is causally related to cardiovascular diseases because lower BDNF levels are associated with various cardiovascular risk factors and metabolic syndromes." (PMID 39648800, 2024). "A heightened presence of saturated fats in red and processed meat has been associated with reduced brain-derived neurotrophic factor, irregular neuroplasticity, and compromised cognitive function—all implicated in depression's pathogenesis." (PMID 38523835, 2024). "Previous studies highlighted the crucial association between pain and depression through the changes in the BDNF-TrkB receptor signaling mechanism." (PMID 38617040, 2024). "Decreased levels of BDNF in the hippocampus are associated with depression and are often seen as comorbidity in IBS and other inflammatory-bowel diseases." (PMID 39839132, 2024). "Some DEGs linked to depression and neuroinflammation (BDNF, CCL2 (Curzytek and Leśkiewicz, 2021), STC1, MEF2C) were also downregulated in Cit200 over time." (PMID 39055655, 2024). "Conversely, antidepressant treatment is associated with an increase in BDNF levels, suggesting a restorative effect on neural circuits impaired by depression." (PMID 39684808, 2024). "Of these, both candidate studies and EWASs report differential BDNF DNAm, as well as associated effects on downstream neurobehavioral outcomes such as depression and anxiety." (PMID 38397427, 2024). "The following limitation of this review is a feature of BDNF related to its gene, whereby there is a polymorphism of a single nucleotide Val66Met that interacts with gender, age and depression, especially in stroke patients." (PMID 38610750, 2024). "A meta‐analysis that included 11 studies showed that BDNF serum level was reduced in patients with depression, and prolonged use of antidepressant drugs was linked with an increase in BDNF serum level." (PMID 37953501, 2024). "BDNF rs6265 has been identified as the cause of several PN symptoms, including anxiety disorders and depression." (PMID 37462904, 2024). "The upregulation of miR-182 reduces BDNF in the hippocampus, further underlining its role in depression pathophysiology." (PMID 38474112, 2024). "The BDNF rs6265 Met/Met genotype was negatively linked with visuospatial working memory capacity with respect to age and depression scores." (PMID 38379321, 2024). "The studies suggest that depression induces neuronal atrophy and loss in limbic regions of the brain, such as the hippocampus, prefrontal lobe, and amygdala, along with a decrease in BDNF expression." (PMID 38389919, 2024). "Some reports indicate a correlation between the severity of depression and BDNF levels, but the association with anxiety scores has been less explored." (PMID 39408702, 2024). "In this study, decreased BDNF increased the risk of Alzheimer’s disease, stress, depression, and anxiety." (PMID 39810851, 2024). "Conversely, in the context of depression, the BDNF Val66Met polymorphism influences the association between life stress and depression, with a more pronounced effect observed for life stress events compared to childhood adversity." (PMID 39935805, 2024). "Our study’s findings of reduced NGF and BDNF expression align with both clinical and animal research, which propose that depression is linked to neuronal degeneration in the hippocampus due to low neurotrophin levels." (PMID 39684342, 2024).
depression (continued). "A recent study demonstrated that inflammation can lead to phenotypes similar to depression by causing changes in brain-derived neurotrophic factor (BDNF), a critical protein involved in synaptic plasticity in the prefrontal cortex, HC, and nucleus accumbens." (PMID 38911248, 2024). "In the ventral tegmental area, BDNF influences reward-related behavior, playing a role in both resilience and susceptibility to depression." (PMID 39684808, 2024). "Since the concentration of this neurotrophic factor in the brain of patients suffering from depression is possible to assess only post-mortem, a diagnostic value has the BDNF level in blood." (PMID 39048810, 2024). "Increased BDNF is associated with reduced inflammation in individuals with depression, while reduced BDNF and increased inflammation are associated with exacerbated symptoms of mood disorders in adolescents." (PMID 39145296, 2024). "BDNF methylation has been linked to adult psychopathology from depression, mood disorders, and personality disorders." (PMID 39295112, 2024). "Both the neurotransmitter serotonin (5-HT) and brain-derived neurotrophic factor (BDNF) are involved in the pathophysiological mechanisms underlying catalepsy and depressive disorders." (PMID 38473717, 2024). "Dysregulation of BDNF is associated with depression, and antidepressant treatments normalize BDNF expression." (PMID 36834565, 2023). "Altogether, our study indicates that BDNF levels in the PFC are associated with maladaptive changes after stress that lead to depression and with adaptive regulation during the confrontation against stress to gain resilience." (PMID 37989582, 2023). "In particular, DNA methylation at multiple CpG sites in stress-related genes (e.g., NRC31, SLC6A4, and BDNF) was associated with depression and partially mediated the association between childhood maltreatment and depression." (PMID 36717542, 2023). "Decreased circulating BDNF has been linked to depression in humans and significantly higher BDNF levels are found after antidepressant treatment in a meta-analysis." (PMID 36205767, 2023). "Decreased BDNF has been linked to the onset of depression, and MeHg-induced depression in mice is reversed by the antidepressant fluoxetine, which increases the levels of BDNF." (PMID 36901772, 2023). "Several neurotransmitter systems, brain-derived neurotrophic factor (BDNF), glial cells, inflammation, and neuroendocrine systems have all been implicated in the development of depression." (PMID 37836833, 2023). "DNA methylation modifications are associated with depression, with hypermethylation at sites encoding BDNF and SLC6A4." (PMID 37140907, 2023). "BDNF plays a crucial role in reducing depression symptoms among older adults and is also associated with memory impairment." (PMID 37422660, 2023). "In light of these discrepancies, some studies conclude that a gene–gene or gene-environment interaction is required for BDNF polymorphism to contribute to major depression." (PMID 34590201, 2023). "Depression, neuronal loss, and cortical atrophy appear to be correlated with lowered levels of BDNF." (PMID 39484176, 2023). "Previously, BDNF, NT-3, and 5-HT have all been implicated in neuroplasticity and have been associated with neuropathological conditions such as anxiety and depression." (PMID 37750080, 2023). "Further, alteration in its DNA methylation levels, assessed by measuring the CpG islands from the Exon IV of the BDNF gene, was shown to be associated with bipolar disorder and major depression." (PMID 38268968, 2023). "L. helveticus R0052 and B. longum R0175 are the most commonly studied probiotics associated with such an effect on the BDNF levels in depression." (PMID 36986112, 2023). "CRTC1, through the regulation of BDNF, has been implicated in multiple neurodegenerative and neuropsychiatric conditions, but the evidence for major depressive disorder is presented below." (PMID 36731029, 2023).
depression (continued). "The neurotrophic theory of depression assumes that environmental stress factors and mutations decrease BDNF synthesis in the brain, resulting in decreased synaptic plasticity, decreased synaptic transmission, and increased neuronal degeneration." (PMID 34590201, 2023). "The purpose of our study was to evaluate plasma levels of BDNF-TrkB signaling, which are inflammatory factors in major depressive disorder (MDD) patients, and assess their associations with clinical performance." (PMID 37626579, 2023). "The HPA axis regulates neurotransmitter release, brain-derived neurotrophic factor abundance, immune responses, and inflammation; all of which have been linked to depression pathogenesis." (PMID 38196849, 2023). "Studies have shown that decreased levels of BDNF are associated with depression, and inflammatory cytokines can decrease the expression of BDNF in the brain." (PMID 37599890, 2023). "Consistent reports have certified that BDNF is associated with the occurrence, development, and management of depression, and it has received the most attention in the neurobiology of depression among any neurotrophic factors." (PMID 37089920, 2023). "It is also possible that BDNF deficiency caused by HPA axis activation increases vulnerability to anhedonia-like symptoms of depression." (PMID 37457896, 2023). "Higher BDNF methylation is independently associated with the prevalence and incidence of depression and major depressive symptoms." (PMID 37091719, 2023). "A higher BDNF promoter methylation status is significantly associated with a suicidal ideation in depression." (PMID 37047638, 2023). "BDNF, a neurotrophic factor whose receptors are crucial in depression pathophysiology, appeared to be implicated in mood symptoms observed in HIV disease." (PMID 38138916, 2023). "Reduction in BDNF level in the hippocampus is reportedly associated with depression, and the BDNF level is reduced in the postmortem brains of patients with depression." (PMID 38082356, 2023). "The investigators also revealed that the neuroplasticity of biomarkers was associated with the degree of depression, and there was a significant increase in brain-derived neurotrophic factor (BDNF) after mindfulness yoga intervention." (PMID 37684609, 2023). "Some studies have shown that the DNA methylation of BDNF mediates the association between childhood trauma and depression to a certain extent, and can be used as an effective diagnostic biomarker for MMD." (PMID 36911124, 2023). "Brain-derived neurotrophic factor (BDNF) has been implicated in the pathophysiological response to depression." (PMID 38249586, 2023). "A review mentioned that DNA methylation modifications are associated with depression, with hypermethylation at sites encoding brain-derived neurotrophic factor (BDNF) and SLC6A4 (5-hydroxytryptamine transporter gene)." (PMID 37140907, 2023). "An emerging body of evidence suggests possible antidepressant effects resulting from probiotic supplementation, which can normalize depression-associated physiological outputs, such as corticosterone, noradrenaline, BDNF, and immune function." (PMID 37139495, 2023). "A number of studies have shown that the deficiency of either CREB or BDNF in the hippocampus results in depression-like behaviors in rodents." (PMID 36731029, 2023). "In numerous animal models, it has been found that depression is closely associated with reduced hippocampal neurogenesis, altered synaptic morphology, and decreased BDNF expression." (PMID 37248634, 2023). "The brain-derived neurotrophic factor (BDNF) Valine 66 to Methionine human polymorphism results in impaired activity-dependent BDNF release and has been linked to psychiatric disorders including depression and anxiety." (PMID 36622381, 2023).